GZMB (granzyme B)
Diseases named in the same sentence as GZMB in open-access papers (continued):
Sharing a sentence is not in itself a finding about the gene and the disease.
COVID-19 (125 papers, 2020 to 2025). A disease caused by infection with severe acute respiratory syndrome coronavirus 2. "It has been reported that PRF1 and GZMB expression in CD8+ T cells increases during COVID-19 progression, potentially causing host cell damage during viral clearance." (PMID 38238762, 2024). "In support of our findings related to IL-6 and granzyme B as biomarkers of liver injury, a recent study demonstrated that IL-6 trans-signaling drives COVID-19-associated hepatic endotheliopathy, which is suggested as a possible mechanism underlying the liver injury." (PMID 35529862, 2022). "Interestingly, NK cells from COVID-19 patients exhibit higher levels of granzyme B that is associated with the severity of the disease." (PMID 35529862, 2022). "In COVID-19, the loss of cytokine production (IL-2, IFNγ or TNFα) and antiviral activity (CD107a and Granzyme B) in both CD4+ and CD8+ T cells may be an important contributing factor to disease severity." (PMID 33575657, 2021). "Several studies have reported elevated serum Granzyme B levels in COVID-19 patients, reflecting the activation of cytotoxic lymphocytes." (PMID 40927375, 2025). "To evaluate the therapeutic potential of granzyme B and neutrophil elastase, we assessed their anti-protease and complement activity in COVID-19 severity using functional mass spectrometry." (PMID 39949890, 2025). "We observed increased levels of neutrophil elastase and granzyme B in patients hospitalized for severe COVID-19." (PMID 39949890, 2025). "Neutrophil elastase and granzyme B were previously identified as significantly elevated in severe COVID-19." (PMID 39949890, 2025). "Compared to COVID-19, LTBI/COVID-19 produced lower levels of perforin and granzyme B at baseline (p<0.05), a pattern that persisted after stimulation with spike and BCG/spike (p<0.05)." (PMID 40458413, 2025). "Immunoassays showed significantly higher levels of neutrophil elastase and granzyme B in severe COVID-19 patients within 48 h of admission, compared to healthy controls." (PMID 39949890, 2025). "During acute COVID-19, cell clusters emerged co-expressing several T cell activation markers including HLA-DR, granzyme B, and CD38." (PMID 41310351, 2025). "Surprisingly Granzyme B expression in NK cells of COVID-19 patients was significantly elevated in moderate (p = 0.02) and severe disease cohorts (p = 0.01) in comparison with healthy controls." (PMID 38212801, 2024). "In contrast, the cytotoxic mediator, granzyme B, was found to be reduced in these groups of COVID-19 patients." (PMID 38855114, 2024). "An increase in the proportion of granzyme-B-expressing NK cells during COVID-19 has been reported in several studies." (PMID 36768315, 2023). "We also observed higher levels of granzyme B+ NK cells in the ICU patient group compared to moderate-severity COVID-19 patients and CCP donors." (PMID 36768315, 2023). "It was reported earlier that, despite the elevated intracellular concentrations of granzyme B, NK cells in COVID-19 are cytotoxically dysfunctional." (PMID 36768315, 2023). "Th17 cells during COVID-19 are characterized by phenotype typical to tissue resident memory T cells also expressing the genes associated with cytolytic potential (SRGN, GZMB, and GNLY) and cytokine genes encoding IL-21, IL-17F, IL-17A, IFN-γ, and GM-CSF." (PMID 37626620, 2023). "It has been demonstrated earlier that patients with COVID-19 shifted towards a cytotoxic phenotype in the T cell compartment, as indicated by high degranulation capacity (granzyme B and perforin levels) compared to healthy controls." (PMID 37240393, 2023). "In summary, the COVID-19 mRNA vaccine elicited central and granzyme B–expressing effector memory CD8 T cells, which were distributed both systemically (spleen) and locally (draining and draining lymph nodes), and in the pulmonary vasculature." (PMID 37796612, 2023).
COVID-19 (continued). "Biomarkers reflective of a stronger cell-mediated antiviral response clearly separated COVID-19 from other CAPs (most notably granzyme B)." (PMID 35660785, 2022). "Trends for higher proportions of IFN-γ-containing CD4+ T lymphocytes and higher granzyme B MFI were observed in COVID-19 patients." (PMID 35422799, 2022). "A correlation matrix for IL-22R+ expressing myeloid cell subsets with the ex vivo IL-22, IL-17A, IFN-γ, granzyme B and perforin expressions on NK and T cells was generated to evaluate a possible relationship between these parameters in COVID-19 patients." (PMID 35422799, 2022). "In this study, the cytotoxic capacity of CD8+ T and NK cells in COVID-19 patients and healthy donors were investigated by detecting perforin, granzyme B, and CD107a expression of these cells." (PMID 36106521, 2022). "Our study also sought to explore the distribution and function of CD4+ T cells expressing cytotoxic molecules such as perforin, granzyme B, CD107a and granulysin in COVID-19 convalescent individuals." (PMID 35336918, 2022). "Severe post-COVID-19 patients exhibited an increased proportion of CD8+ cells producing Granzyme B together with IFN-γ upon long recovery, suggesting the persistence of a strong cytotoxic T cell responses." (PMID 35757700, 2022). "In detail, the frequency of GzmA+GzmB+perforin+ cells co-expressing lung-homing receptors was commonly strongly increased in patients, except for CD56dimCD16+ NK cells in COVID-19 patients." (PMID 35371005, 2022). "When stimulated with cytokines IL-12 and IL-18, impaired upregulation of IL-17A, TNFα, granzyme B and perforin was observed in the COVID-19 cohort, and a reduction in perforin was observed." (PMID 34050887, 2022). "Increased IL-6 and granzyme B were found to predict liver injury in COVID-19 patients, whereas interferon-gamma (IFN-γ), IL-1 receptor-a (IL-1Ra) and PD-L1 were predictors of remarkable radiological findings." (PMID 35529862, 2022). "In COVID-19, the most significantly increased biomarker was granzyme B, an apoptosis-mediating serine protease that is mostly produced by natural killer cells and cytotoxic T cells, critical for eliminating virus-infected cells." (PMID 35660785, 2022). "In the literature, NK cell counts and perforin, granzyme B levels were reported to be decreased in COVID-19 patients." (PMID 36110850, 2022). "Decreased production of CD107a+, IFN-γ+, IL-2+, and granzyme B+ was also described in CD8+ T lymphocytes in COVID-19." (PMID 36359755, 2022). "The transmembrane glycoprotein CD40 ligand and the cytotoxic molecule granzyme B showed a significant increase in mild-moderate COVID-19 patients compared to healthy controls." (PMID 35529862, 2022). "There was an apparent increase in the levels of perforin and granzyme B in NK cells from COVID-19 patients that correlated with the disease severity." (PMID 33777054, 2021). "NKT-like cells have increased production of Granzyme B and perforin and their numbers are similar to healthy controls in mild disease, expanded in moderate COVID-19, and decreased in severe disease." (PMID 33575657, 2021). "This evidence of enhanced expression of cytotoxic NK subpopulations was further supported by elevated serum levels of sFas granzyme B and perforin that we found in our COVID-19 cohort." (PMID 34831404, 2021). "While our findings show a substantial decrease in granzyme B production in MAIT cells of COVID-19 patients, these studies show an increase in granzyme B expression by MAIT cells in SARS-COV2 infected patients." (PMID 34238985, 2021). "Results showed that both CD56bright and CD56dim NK cells from COVID-19 patients exhibited higher levels of perforin and granzyme B as determined by the MFI of these markers." (PMID 33777054, 2021). "Nevertheless, the expression of perforin and granzyme B was higher in each adaptive NK cell subset from COVID-19 patients when compared with HC." (PMID 33777054, 2021).
COVID-19 (continued). "When we probed cytokine (i.e. IL-12 and IL-18)-mediated MAIT cell activation, MAIT cells from COVID-19 patients showed an altered cytokine expression profile characterised by impaired upregulation of IL-17A, TNFα, granzyme B and perforin." (PMID 33546489, 2021). "MAIT cell frequencies and expression of IFN-γ, granzyme B and CD107a were reduced in people with COVID-19/bacterial coinfection, potentially suggesting a functional consequence of this impairment." (PMID 35381137, 2021). "In vitro studies showed that MAIT cell IFN-γ and granzyme B production were impaired by coculture with CD14+ cells from patients with severe COVID-19 and this is mediated by monocyte-derived IL-10 and IFN-α." (PMID 35381137, 2021). "This Th1 cytokine or granzyme B producing T cell response is comparable to what is seen healthy individuals but clearly inferior to COVID-19 patients." (PMID 34228322, 2021). "In particular, IL-6 directly reduces the expression of perforin and granzyme B. In patients with COVID-19 admitted to the intensive care unit, an inverse correlation between serum levels of IL-6 and NK cells’ frequency of expressing granzyme A was found." (PMID 33669527, 2021). "NK4 cells in COVID-19 exhibited cytolytic potential with increased expression of granzymes (GZMB and GZMA) and expressed CD56." (PMID 34721400, 2021). "The levels of serum cytokines such as IL-6, IL-10, perforin, granulysin, sFas, and granzyme B in COVID-19 patients were significantly higher than those in healthy controls." (PMID 33154753, 2020). "Immunoassay quantification of these proteases in serum indicate that within 48 h of admission, severe COVID-19 patients had significantly higher levels of neutrophil elastase (median 71.8 pg/mL versus 2.8 pg/mL; p > 0.001) and granzyme B (median 8.0 pg/mL versus 2.3 pg/mL; p = 0.006)." (PMID 39949890, 2025). "However, LTBI/COVID-19 displays lower soluble levels of granzyme B and perforin in culture supernatants and perforin, granulysin, and sFas in plasma compared to COVID-19." (PMID 40458413, 2025). "In addition, a slight reduction in % NK Granzyme B+ is shown in COVID-19 women compared to Control-LS women (P = 0.0094)." (PMID 41573558, 2025). "Patients with comorbid COVID-19 and T2D exhibited significantly reduced expression of cytotoxic mediators (GZMB, perforin and IFN-γ) alongside elevated IL-6 levels compared with other groups, demonstrating a synergistic impairment of NK cell effector function in the dual-pathology cohort." (PMID 40471558, 2025). "Moreover, NK cells from COVID-19 patients exhibited increased Granzyme B expression, with CD56bright NK cells showing a median of 87.41% (IQR: 82.78-92.34, P<0.0001), which was 10% higher than that observed in Control-LS individuals." (PMID 41573558, 2025). "Notably, Granzyme B and Perforin were predicted downstream targets of ligands expressed by monocytes in severe COVID-19." (PMID 38578283, 2024). "Surface expression of the activating receptor NKG2D and the activating coreceptor DNAM-1 were decreased in COVID-19 patients compared with healthy controls while having greatly increased intracellular expression of the cytotoxic molecules Granzyme B and Perforin and the proliferation marker Ki-67." (PMID 38578283, 2024). "In addition, the combination of SAMD9, GZMB, JUNB, and NR4A1 presented excellent diagnostic value in COVID-19." (PMID 38384322, 2023). "The percentage of NKT-like cells with cytotoxic phenotype CD3+CD56+CD16+ was observed to be increased in patients with critical COVID-19, while the proportion of these cells expressing granzyme B was decreased in ICU patients along with a decrease in their cytotoxicity." (PMID 37240393, 2023). "Additionally, we examined changes in the most cytotoxic CD8+CD56+ subset level and granzyme B expression in T cells against the background of COVID-19." (PMID 37240393, 2023).
COVID-19 (continued). "The increase in granzyme B levels in NK cells may be partially mediated by pro-inflammatory cytokines actively produced during COVID-19, such as IL-15." (PMID 36768315, 2023). "(2012), IL-17+ Tregs may have been partially responsible for the higher expression of perforin and granzyme B found in the Mild Recovered group and probably contributed to the mildness of the disease in these volunteers during acute COVID-19." (PMID 36969257, 2023). "Finally, the increased proportion of CD8+ cells producing Granzyme B together with IFN-γ was specifically characteristic for severe post-COVID-19 patients at time II, indicating unresolved inflammation." (PMID 35757700, 2022). "Contracting Covid‐19 was associated with SARS‐CoV‐2‐specific neutralizing serum IgG, T cell, IFN‐γ, and granzyme B responses to SARS‐CoV‐2, self‐reported typical Covid‐19 symptoms, male sex, higher BMI, and hypertension." (PMID 35128644, 2022). "Moreover, COVID-19 patients were reported to have reduced NK cell functional markers such as CD107a+ (a degranulation marker), granzyme B, IFN-γ+, IL-2+, and TNF-α+ compared to healthy controls." (PMID 35273641, 2022). "Moreover, IFN-γ, IL-1Ra were predictors of remarkable radiological findings, whereas high IL-6 and granzyme B were found to predict liver injury in COVID-19 patients." (PMID 35529862, 2022). "However, we did observe increased GZMB expression in the CD8+ T cells as well as increased density of Lin–GZMB+ cytotoxic cells in all the COVID-19 mortality cases." (PMID 35446789, 2022). "Known markers of CD8+ T cell activation (T-bet, Ki-67, CD69, TOX, and GZMB) were significantly increased in baseline COVID-19 patients compared to HD, supporting our hypothesis that SARS-CoV-2 infection increases peripheral T cell activation." (PMID 35012610, 2022). "In a multivariable linear regression model of the COVID-19 cases, the expression of GZMB in the CD8+ T cells was found to be a significant predictor of lower alveolar epithelial cell density after adjustment for confounding factors including age, presence of ALI, and length of symptomatic interval." (PMID 35446789, 2022). "Furthermore, it has been reported that Perforin, GZMB and Granulysin expression levels were upregulated in the acute phase of mild COVID-19 patients compared to moderate and severe patients." (PMID 36685601, 2022). "Only granzyme B was secreted from T cells in greater amounts by females than by males in this study, suggesting stronger cytotoxic responses in females than males during the memory phase after the second COVID-19 vaccination." (PMID 35572546, 2022). "Recent studies have reported that during acute SARS-CoV-2 infection, NKT-like cells showed a significant increase in GzmB and perforin production, as well as a decrease in numbers in severe COVID-19 cases, suggesting these cells are highly activated during the acute phase." (PMID 33906918, 2021). "Finally, we investigated if the production of granzyme B, a primary cytotoxic mediator, distinguished COVID-19 patients depending on the severity of the disease." (PMID 34745145, 2021). "To further investigate the effect of SARS-CoV-2 infection on MAIT cell function, we quantified the frequencies of MAIT cells expressing cytokines (IFN-γ and TNF-α) and cytolytic molecules (granzyme B and perforin) in 8 uninfected individuals and 7 COVID-19 patients." (PMID 34238985, 2021). "Moreover, granzyme B and perforin levels were produced at similar levels in the final cell products from both unexposed and COVID-19 recovered individuals." (PMID 35003063, 2021). "MAIT cells isolated from COVID-19 patients expressed significantly higher levels of the pro-inflammatory cytokines TNFα and IL-17A, as well as of the cytolytic protein granzyme B compared to healthy controls ex vivo, while ex vivo expression of IFNγ and perforin was unchanged." (PMID 33546489, 2021).
COVID-19 (continued). "IL-7 treatment did not significantly increase the frequency of MAIT cells expressing TNF-α or granzyme B in COVID-19 patients, but it successfully increased both the perforin expression level (MFI) (p = 0.001) and the frequency of MAIT cells expressing perforin (p = 0.001)." (PMID 34238985, 2021). "Interestingly, decreased expression of both PRF1 and GZMB hub-high traffic genes in severe COVID-19 patients lead to dysfunction of NK cells cytotoxicity, indicating that both genes are essential for NK cells activity." (PMID 34975885, 2021). "Consistently, another study found that the levels of tumor necrosis factor-α (TNF-α) and IFN-γ in CD4+ T cells of severe COVID-19 patients were lower than those of mild patients, while the levels of granzyme B and perforin in CD8+ T cells of severe patients were higher than those of mild patients." (PMID 33987176, 2021). "Other studies also reported increased PRF1, GNLY, soluble Fas, and GZMB in COVID-19 patients." (PMID 34945761, 2021). "High expression of perforin and granzyme B in severe COVID-19 cases could suggest some role for host immune response in exacerbating disease." (PMID 33133083, 2020). "Therefore, whether the postvaccination upregulation of KLRD1 expression can confer protection by promoting the expressions of GZMB and PRF1, and whether KLRD1 expression is related to COVID-19 susceptibility needs to be clarified." (PMID 37654490, 2023). "Therefore, we examined whether perforin or granzyme B positivity correlated with age in our COVID-19 patients." (PMID 36817450, 2023). "Notably, aged CD8+ T cells had a striking decrease in granzyme B production, a phenomenon that has been described for other aged mouse models using single cell RNA sequencing analysis as well as in elderly humans infected with COVID-19." (PMID 37528458, 2023). "CoV-2 infection of IECs stimulated robust IFN-γ, Granzyme B, TNF-α production in MAIT cells." (PMID 36825215, 2022). "An ex vivo study of NK cells from the peripheral blood of patients with COVID-19 revealed a decrease in the expression of CD107a, caspase Ksp37, granzyme B, and granulysin; these changes could result in reduced cytotoxicity and insufficient production of IFN-γ and TNF-α." (PMID 34603758, 2021). "Our results demonstrate an overexpression of the functional markers IFN-γ and Granzyme B, as well as the inhibitory receptor KIR2DL1, on peripheral blood NK cells from severe COVID-19 patients, compared to uninfected controls." (PMID 40927375, 2025). "Cytotoxic TFH subpopulations with perforin and granzyme B expression have been detected among CD4+ T cells in children with group A Streptococcal recurrent pharyngitis (GAS RT) and in severely ill COVID-19 patients among virus-specific CD4+ T cells." (PMID 39025930, 2024). "The levels of COVID-19 microenvironment markers, i.e., CD3, CD4, CD8, CD20, CD68, vimentin, NP, ACE2, Granzyme B, E-cadherin, and phosphorylated nuclear factor kappa B (p-NFκB), were measured via IMC." (PMID 39100091, 2024). "Specifically, compared to healthy controls, genes marking effector and cytotoxic CD8 T cell profiles (GZMB, NKG7, GZMH, PRF1, and CCL5) were upregulated in severe dengue and downregulated in severe COVID-19." (PMID 38294906, 2024). "Another study found that young COVID-19 patients had greater percentages of CD8+ T cells expressing perforin, granzyme A, and granzyme B compared to healthy controls of the same age, but the same difference was not seen in elderly COVID-19 patients." (PMID 36817450, 2023). "Similar to GZMA, PRF1, GZMK and GZMB in T cells, significant increases in CASP3 were also present in COVID-19 patients with encephalopathy, and the highest expression of this gene was observed in acute necrotizing encephalopathy patients." (PMID 37848421, 2023). "COVID-19 patients with encephalopathy had significant overexpression of various cytotoxic genes, including PRF1, GZMK, GZMA, GZMB, GNLY, and CST7." (PMID 37848421, 2023).